INS (insulin)
Diseases named in the same sentence as INS in open-access papers (continued):
Sharing a sentence is not in itself a finding about the gene and the disease.
Hypoglycemia (continued). "Hypoglycemia is a common adverse effect of treatment of T2DM with insulin and sulphonylureas." (PMID 29121919, 2017). "Renal injury may additionally aggravate hypoglycemia through decreased insulin degradation and gluconeogenesis." (PMID 28245289, 2017). "Out of the patients who performed SMBG, 63.4% (n=210) made alterations to their treatment regimen (adjustment of insulin or skipping oral dose to avoid hypoglycaemia) and lifestyle (carbohydrate intake, physical exercise and consultation of physician for advice)." (PMID 28698830, 2017). "The hypoglycemia effect of the MTPE could be attributed to its ability to restore the function of pancreatic tissues by increasing insulin output, inhibiting the intestinal absorption of glucose, or enhancing metabolism of insulin-dependent processes." (PMID 28529969, 2017). "This suggests that, unlike other long-acting insulin formulations, insulin degludec does not increase the risk for nocturnal hypoglycemia even when its dose is adjusted to target fasting glucose levels between 80 and 100 mg/dL." (PMID 28683068, 2017). "Adverse effects associated with canagliflozin in initial safety trials include increased incidence of genitourinary infections, increased serum creatinine, hypoglycemia when administered with sulfonylureas or insulin, and hyperkalemia in patients with chronic kidney disease." (PMID 29978156, 2017). "Daytime use of closed-loop insulin delivery increased time spent with glucose concentration in the target range by 8·1 percentage points (95% CI 5·3–11·0, p<0·0001) and reduced the burden of hypoglycaemia by 61% (14–75, p=0·0001)." (PMID 28094136, 2017). "Additionally, insufficient glucagon response to hypoglycemia in diabetic patients was shown to be normalized by the maintenance of long-term (1 to 3 months) adequate glycemic control using intensive insulin therapy." (PMID 28426798, 2017). "This study investigated whether glycogen‐derived fuel supply is a critical screened variable in ventromedial hypothalamic nucleus (VMN) monitoring of neuro‐metabolic stability during glucostasis and/or insulin (I)‐induced hypoglycemia." (PMID 29199177, 2017). "The hypoglycaemia-induced hyperphagia despite hyperinsulinaemia has been shown before, indicating that, with regard to control of appetite, the glucose availability dominates over insulin and leptin signalling, at least initially in the present model." (PMID 28421113, 2017). "Oral therapy with insulin secretagogues (sulfonylurea and glinides) may also be considered as second-line therapy, but should be aware of hypoglycemia in patients with inconsistent meal ingestion." (PMID 28101143, 2017). "The use of short-acting insulin may be a third factor involved in the development of a low incidence of hypoglycemia in our study." (PMID 28245289, 2017). "Confirmation of diagnosis is usually obtained by showing an association of hypoglycemia with non-suppressed insulin secretion during normal or prolonged fasting." (PMID 28427440, 2017). "Meglitinide combined with insulin will increase hypoglycemia in patients with advanced CKD." (PMID 29100450, 2017). "After a thorough hypoglycemia workup revealed no other cause, it was felt that etanercept had improved insulin sensitivity by decreasing inflammation, which led to recurrent mild hypoglycemia due to a likely relative hyperinsulinism from T2DM." (PMID 29721512, 2017). "On the other hand, hypoglycemia tended to occur more frequently among those in the hypoglycemia group who were injected with insulin degludec in the evening or before bedtime (eleven patients, 68.7%), compared to those who did so in the morning (five patients, 31.3%)." (PMID 28683068, 2017). "The ideal adjunct therapy would, therefore, reduce insulin dose requirement, lower HbA1c without increasing the risk of hypoglycaemia, reduce weight, and have direct effects to reduce the risk of cardiovascular disease and improve life expectancy." (PMID 28770327, 2017).
Hypoglycemia (continued). "Thus, increased lipid oxidation can occur in the brain of rats and mice already after a single episode of insulin-induced hypoglycaemia if the hypoglycaemia is severe enough." (PMID 28421113, 2017). "SGLT2 inhibitors are unlikely to pose a risk of inducing hypoglycemia because they do not stimulate insulin secretion or inhibit counter-regulatory response during hypoglycemia." (PMID 28785316, 2017). "Also, plasma insulin concentrations are inappropriately high at the time of hypoglycemia, indicating dysregulation of insulin secretion as an important mechanism." (PMID 28298900, 2017). "Insulin should be used very carefully and only as an infusion since hypoglycemia may lead to life-long neurodevelopmental impairments." (PMID 28487864, 2017). "Reversely, naturally occurring hypoglycaemia induced by fasting is typically accompanied by a decrease in plasma insulin and leptin levels and increased neuronal GLUT3 levels, presumably to compensate for restricted supply of glucose from peripheral circulation." (PMID 28421113, 2017). "However, iPro2 indicated a trend towards a difference in the time spent in hypoglycaemia during 1000 h of insulin infusion and the number of patients experiencing at least one hypoglycaemia event." (PMID 28699150, 2017). "While severe hypoglycemia remains a major clinical problem, particularly for people treated with insulin, this may be declining in some patient groups." (PMID 28824815, 2017). "The advent of continuous glucose monitoring (CGM) that can alert and warn patients of impending hypoglycemia and, in particular, systems that integrate CGM data CSII systems capable of suspending insulin delivery in the presence of sensor-detected hypoglycemia have made a huge difference." (PMID 28293906, 2017). "However, the incidence of severe hypoglycemia was similar for the pramlintide and insulin groups in the studies included in the present analysis." (PMID 28702246, 2016). "Similarly, leptin receptor mRNA expression, counter regulatory responses to insulin-induced hypoglycemia, and central insulin signaling have all been observed to be lower in the inbred line of DIO rats compared to DR rats." (PMID 27933296, 2016). "We confirmed significant hypoglycemia with suppression of endogenous insulin secretion." (PMID 27957352, 2016). "Programmable insulin administration in basal and bolus fashion is integrated and augmented with glucose biosensors to provide real-time, data-driven glycemic control and early detection of hypoglycemia." (PMID 26742082, 2016). "However, after physicians were allowed to titrate the insulin dose, the incidence of hypoglycemia over the complete 78-week treatment was similar among the groups." (PMID 27316668, 2016). "A 2-h intra-arterial infusion of either glucagon or epinephrine increased plasma concentrations (within the physiologic range experienced during acute hypoglycemia or stress (13, –, 15)) also raised plasma glucose by 5–8 mm with corresponding increases in plasma insulin." (PMID 27002151, 2016). "A possible explanation could be that the increased hypothalamic expression of pAMPK, following insulin injection in the CD group and in the FD group, was mediated by hypoglycemia in agreement with previous findings that hypoglycemia activates AMPK." (PMID 27375435, 2016). "A lower total incidence of drug-related treatment-emergent adverse events (TEAEs) was reported for patients in the insulin glargine group, compared with the NPH insulin group;the most common drug-related TEAEs were hypoglycaemia (33.6% versus 40.7%) and weight gain (0.9% versus 1.9%)." (PMID 27887605, 2016). "Plausible mechanisms by which hypoglycaemia might occur is the stimulation of insulin secretion as reported by Nunnari and al. and Strevel and al., suggesting a sulfonylurea-like mechanism." (PMID 27927207, 2016).
Hypoglycemia (continued). "However, the time spent in hypoglycemia (<3.9 mmol/L) (%) detected by CGM was significantly decreased by the use of transient insulin intensive treatment either in newly diagnosed or in advanced T2DM patients compared with the baseline before treatment." (PMID 26839889, 2016). "However, subcutaneous administration of insulin reportedly produced variable depth and length of hypoglycaemia when compared to i.p administration." (PMID 27843452, 2016). "Furthermore, analysis of the tumor failed to reveal the presence of insulin, thus leading to the conclusion that the hypoglycemia was non-insulin mediated." (PMID 27905899, 2016). "These components may potentially represent the BG measurements taken from patients with hypoglycaemia, or patients who were fasting or receiving insulin infusions." (PMID 27059020, 2016). "As plasma glucose falls below levels that can be reversed by responses at the level of pancreatic islets, i.e. suppression of insulin release and stimulation of that of glucagon, the brain’s sensing abilities are activated to allow timely detection of hypoglycemia." (PMID 26521082, 2016). "For the scenario of insulin-induced hypoglycemia, we evaluated whether CoQ10 could play a protective role in the peripheral nerves." (PMID 26824041, 2016). "Various abnormalities related to glucose homeostasis, such as hypoinslulinemia, hypoglycemia, increased insulin sensitivity, decreased serum growth hormone level and reduced hepatic IGF-1 expression, could be observed in mutant animals before death." (PMID 27293546, 2016). "Systemic administration of insulin is obviously undesirable because it is difficult to enter into the brain and would otherwise disturb metabolism in the periphery and may lead to hypoglycemia." (PMID 26879001, 2016). "Additionally, rat models of insulin-induced hypoglycemia have shown the therapeutic potential of PAPD-1 inhibitors." (PMID 26824041, 2016). "Fear of hypoglycemia, weight gain, pain associated with blood testing and injection-related pain are the most cited reasons for not starting insulin therapy." (PMID 26740822, 2016). "Secondary outcomes including the change in hypoglycemia events, insulin doses and BMI." (PMID 27841330, 2016). "The drawbacks of insulin are as follows; it needs health education, needs many daily subcutaneous injections, and requires dose modification depending on body mass index of patient, occurrence of hypoglycemia, and gaining weight in mother." (PMID 27597988, 2016). "Since 2008, two other very promising therapeutic classes have been placed on the market: dipeptidyl peptidase-4 (DPP-4) inhibitors and glucagon like peptide 1 (GLP-1) analogues to promote insulin secretion without the risk of hypoglycemia." (PMID 28105440, 2016). "However, this insulin presents higher interindividual variability, higher incidence of hypoglycemia episodes and worse glucose control when compared with NPH." (PMID 26740822, 2016). "Test results indicate that paliperidone induced hypoglycemia by increasing insulin secretion." (PMID 27478670, 2016). "In our study, discontinuing benzodiazepines known to cause hypoglycemia did not alleviate our patient's hypoglycemia, but reducing the dose of paliperidone (an active metabolite of risperidone) effectively resolved her persistent hypoglycemia by dampening insulin release." (PMID 27478670, 2016). "Whereas the mechanism by which insulin may contribute to CVD risk or mortality is unclear, several investigators have shown that insulin-associated hypoglycemia is also associated with cardiac arrhythmias." (PMID 27188479, 2016). "Although insulin analogs are more expensive to the payer than human insulin, insulin analogs may be able to reduce more expensive long-term expenditures such as the costs related to treatment of hypoglycemia or chronic complications of DM." (PMID 27278922, 2016).
Hypoglycemia (continued). "However, glucose lowering medications in T2D can upset the homeostatic balance between blood glucose and insulin levels, resulting in the development of hypoglycaemia." (PMID 27305000, 2016). "We evaluate herein retinal gene expression 4 h and 48 h after insulin-induced hypoglycemia." (PMID 26918849, 2016). "In addition to hypoglycemia, we recorded extremely low level of serum insulin and elevated insulin sensitivity in the mutants." (PMID 27293546, 2016). "However, because insulin suppresses the production of ketones, the brain is usually unable to use this source of energy during insulin-induced hypoglycemia." (PMID 26521082, 2016). "Another possibility is that the increased basal insulin may result in experienced or perceived hypoglycemia." (PMID 27777901, 2016). "If hypoglycemic episodes are occurring and insulin continues to be necessary, sulfonylurea should be replaced by another medication that does not cause hypoglycemia." (PMID 27546934, 2016). "In fact, some computerized protocols also make recommendations as to the nutritional rates the patients should be receiving so that hypoglycemia, and perhaps increased GV, may be avoided if the insulin infusion rate is changed." (PMID 26819233, 2016). "Some of the increases in FPG observed at 3 months post-baseline may have been due to decreases in insulin to avoid hypoglycemia." (PMID 27642538, 2016). "Application of high doses of insulin to genetically at-risk healthy children without signs of islet autoimmunity promoted an immune response without hypoglycemia." (PMID 26975663, 2016). "Notably, Poland provides long-acting insulin analogues, but only for patients with severe hypoglycemia episodes." (PMID 27907034, 2016). "Compared with insulin, the risk of hypoglycemia associated with non-insulin therapies is lower and is generally limited to secretagogues." (PMID 26972690, 2016). "Physician barriers include fears for their patients’ safety (including weight gain and hypoglycemia), a perceived greater drain on physician’s resources (time and cost), and concern that insulin regimens are too complex for patients to understand and will result in poor adherence." (PMID 27453733, 2016). "However, severe hypoglycaemia was more frequent with insulin compared to hypoglycaemic drugs RR = 1.70 (95 % CI = 1.51–1.91)." (PMID 27391319, 2016). "Unfortunately, current insulin options do not fulfill the main requirements for ideal basal insulin: flat PD profile, with low hypoglycemia risk, 24 h duration, and low interindividual variability." (PMID 26740822, 2016). "Therefore it is conceivable that the increased insulin is driving the hypoglycemia which is resulting in over eating and excessive caloric intake." (PMID 27777901, 2016). "Lower insulin levels in the fetus may also result in less neonatal hypoglycemia and fewer NICU admissions." (PMID 27435163, 2016). "For example, hypoglycemia is a common acute complication of insulin treatment, yet in this age group (and in parents) in Australia, we know little about the frequency and severity of hypoglycaemia, impaired awareness of hypoglycaemia and the impact of hypoglycaemia on emotional well-being." (PMID 27519408, 2016). "assessed the incidence of hypoglycemia in 36 patients at six postoperative months of Roux-en-Y gastric bypass or more; those authors used a test with 100 g dextrosol and hourly blood glucose and insulin measurements over the course of four hours." (PMID 26910630, 2016). "In our study, we found that symptomatic hypoglycemia tend to occur with insulin-treated patients." (PMID 27246619, 2016). "Anti-insulin IgG antibodies have often been reported to induce hypoglycemia." (PMID 27456688, 2016). "Incidence rates of drug-induced hypoglycemia were highest for basal insulin and oral sulfonylurea agents in 65–79 year olds (8.64 and 4.32 events per person-year, respectively), and even higher for octogenarians (12.06 and 6.03 events per person-year, respectively)." (PMID 27648831, 2016).
Hypoglycemia (continued). "On the other side, the steep rise in glucose levels could be interpreted as a meal and lead to excessive insulin and hypoglycemia." (PMID 30740333, 2016). "Exaggerated and long-lasting reduction of insulin dose, that might result from the fear of hypoglycemia, leads to high pre-exercise glucose levels, which accounts for the absence of the reduction in HbA1c levels." (PMID 27517956, 2016). "Similarly, when a subject is likely to be sleeping (which can be inferred from a 3-axis accelerometer), the insulin delivery is less aggressive, but again targeting a low probability of hypoglycemia." (PMID 30740333, 2016). "Both C/EBPβ–/–mice and PDK4–/–mice display hypoglycemia and increased insulin sensitivity." (PMID 27711113, 2016). "In terms of GV and hypoglycemia, the inferior performance of SQ Lispro insulin was a result of its shorter duration of action; thus, SQ Lispro insulin may not be the best choice for patients who are continually postprandial." (PMID 26819233, 2016). "Atypical antipsychotics might antagonize muscarinic receptors so that insulin secretion continues after glucose levels return to normal, leading to hypoglycemia." (PMID 27478670, 2016). "Two strains of mice were used and 1 unit/kg of insulin was given to induce hypoglycemia." (PMID 26824041, 2016). "There was no statistical association between being on insulin and knowledge of hypoglycaemia or how to manage hypoglycaemia." (PMID 27380786, 2016). "NICTH should be considered when hypoglycemia occurs in the setting of low serum insulin levels." (PMID 27905899, 2016). "Furthermore, insulin glargine has been associated with better control of fasting blood glucose (FBG) levels, lower incidence of hypoglycaemia,and nocturnal free insulin levels." (PMID 27887605, 2016). "It acts on pancreatic β-cells, releasing insulin, and in pancreatic α-cells, inhibiting the secretion of glucagon in a glucose-dependent manner; therefore, GLP-1 controls blood glucose with a lower risk of hypoglycemia." (PMID 27471550, 2016). "We reasoned that this might be due to either a primary hypoglycemia with a secondary hypoinsulinemia, and/or a primary action of insulin to more efficiently lower glycemia." (PMID 27148080, 2016). "Because of poor organ function, the half-life of insulin could be prolonged and result in late hypoglycaemia.In this case, a low-normal blood sugar level was found in the 2nd hour after discontinuation of the intravenous regular insulin." (PMID 26939866, 2016). "The most remarkable finding in this subsection was that SQ Lispro insulin (but not regular insulin) caused hypoglycemia (glucose concentrations near 60 mg/dL)." (PMID 26819233, 2016). "Basal insulin and sulfonylureas are not cost-effective agents with respect to hypoglycemic events and associated hypoglycemia-related quality of life." (PMID 27648831, 2016). "Further reduction or suspension of insulin delivery coupled with ingestion of carbohydrate beforehand may be necessary, with further carbohydrate supplementation to avoid hypoglycaemia, depending on prevailing blood glucose levels during and after exercise." (PMID 27287376, 2016). "It is important to note that with once-nightly injection of a basal insulin analog, one cannot obtain a flat baseline glucose level during the dawn phenomenon period without increasing the risk for hypoglycemia during the non-dawn periods." (PMID 27457238, 2016). "The last quarter century has witnessed remarkable advances in replicating the natural pancreas function with insulin pump devices based on increasingly accurate sensing, precise delivery, reduction in glycemic excursions, and inherent safeguards against hypoglycemia." (PMID 26742082, 2016). "Glucagon, rapidly released in response to an insulin-induced hypoglycemia, may serve as a common link to unify results obtained with ITT and GST as previous data suggest that glucagon is rapidly released following ITT." (PMID 26578365, 2016).